MRC2 (mannose receptor C-type 2)
Diseases named in the same sentence as MRC2 in open-access papers (continued):
Sharing a sentence is not in itself a finding about the gene and the disease.
meningioma (1 paper, 2020). A generally slow growing tumor attached to the dura mater. "As per the heatmap it is visible that NDRG1, MRC2, and COPS8 is highly abundant in the higher grades of meningiomas whereas more abundances of COL14A, COL12A1 were found in the non-tumor controls." (PMID 32974197, 2020).
Obesity (1 paper, 2023). Accumulation of substantial excess body fat. "Out of the 5 genes identified as optimal predictors, 3 (ie, CDIPT, MRC2, and SUMO3) have been previously shown to be associated with T2D or obesity." (PMID 37040172, 2023).
ovarian carcinoma (1 paper, 2021). A malignant neoplasm originating from the surface ovarian epithelium. "Therefore, we highlight that the LINC00909/miR-23b-3p/MRC2 axis is implicated in the pathogenesis of ovarian cancer, and serum LINC00909 may be a promising biomarker for the diagnosis of OC." (PMID 34336102, 2021). "Therefore, our observations collectively demonstrated that LINC00909 achieves oncogenic functions in ovarian cancer cells via regulating MRC2." (PMID 34336102, 2021). "Interestingly, we found that, in the ovarian cancer RNA expression datasheet from the GEPIA database, ZNF839, DEPDC1, and MRC2 were associated with LINC00909 in the RNA level." (PMID 34336102, 2021). "In a mechanism, we demonstrated that the elevated LINC00909 level in ovarian cancer cells upregulates the expression of MRC2 by sponging miR-23b-3p and thereby promotes cell proliferation, migration, invasion, and EMT of ovarian cancer cells." (PMID 34336102, 2021). "In mechanism, the elevated LINC00909 level in ovarian cancer cells upregulates the expression of MRC2 by sponging miR-23b-3p, and thereby promotes cell proliferation, migration, invasion, and EMT of ovarian cancer cells." (PMID 34336102, 2021). "Altogether, our findings demonstrated that LINC00909 is a ceRNA of MRC2, LASP1, and ZNF839 mRNA in the mediation of miR-23b-3p in ovarian cancer cells." (PMID 34336102, 2021). "To further investigate the relation between LINC00909 and MRC2 in ovarian cancer cells, we overexpressed LINC00909 in MRC2 knockdown OVCAR4 cells." (PMID 34336102, 2021). "Meanwhile, our findings revealed that MRC2, LASP1, and ZNF839 were upregulated in ovarian cancers, especially in the subtype of serous ovarian cancer." (PMID 34336102, 2021). "Besides, we demonstrated that LINC00909 functions as a competing endogenous RNA (ceRNA) of MRC2 mRNA by sponging miR-23-3p, and thereby promotes epithelial-to-mesenchymal transition (EMT) of ovarian cancer cells." (PMID 34336102, 2021).
prion disease (1 paper, 2014). A transmissible disease that is caused by a protein that is able to induce abnormal folding of normal cellular proteins, leading to characteristic spongiform brain changes, which are associated with neuronal loss without an inflammatory response. "We have demonstrated that loss of Cx3cr1 results in an acceleration of onset of prion disease with three distinct prion strains (Chandler/RML, ME7 and MRC2) suggesting that intact Cx3cl1/Cx3cr1 signalling is partially protective in prion disease." (PMID 24655482, 2014).
psychosis (1 paper, 2022). "Also, in a GWAS, the MRC2 gene was associated with “psychosis proneness”." (PMID 35546954, 2022).
rectal cancer (1 paper, 2015). A primary or metastatic malignant neoplasm that affects the rectum. "The biomarker signature was comprised of seven proteins (CADM1, LGALS3BP, HYOU1, FN1, VTN, LRG1, and MRC2) (Fig4A) that could predict the localization of rectal tumors especially well (86% of subjects with rectal cancer)." (PMID 26253080, 2015).
schizophrenia (1 paper, 2022). A major psychotic disorder characterized by abnormalities in the perception or expression of reality. "The biomarkers identification showed specific and sensitive results for schizophrenia, where two proteins (PRL and MRC2) produced adequate results." (PMID 35546954, 2022).
tuberculosis (1 paper, 2018). A chronic, recurrent infection caused by the bacterium Mycobacterium tuberculosis. "Previous studies were able to identify tuberculosis-associated variants in a few CTLR genes in different populations, such as for MRC2, MBL, or MASP2 in Chinese populations, DC-SIGN variants in African populations, and several variants of SPA-1, SPA-2, or MBL in diverse populations." (PMID 29515573, 2018).
urothelial carcinoma (1 paper, 2022). A malignant neoplasm derived from the transitional epithelium of the urinary tract (urinary bladder, ureter, urethra, or renal pelvis). "Additionally, the therapy response with different MRC2 expression levels to immunotherapies for melanoma and urothelial carcinoma was further investigated according to the public immunotherapeutic cohorts." (PMID 36188226, 2022).
uveitis (1 paper, 2025). An inflammatory process affecting a part of or the entire uvea. "Among these, the Major Histocompatibility Complex (MHC) class II and the enzyme Arginase 1 (ARG1) were significantly enriched in RMG from uveitis-affected horses, whereas Mannose Receptor C-type 2 (MRC2) and its interactor Thrombospondin 1 (THBS1) were more abundant in healthy RMG." (PMID 40001591, 2025). "We investigated the spatial distribution and expression of MRC2 in healthy retinas (DIC) and retinas from uveitis cases (DIC)." (PMID 40001591, 2025). "These molecules significantly decrease in RMG from healthy retinas, while MRC2 is highly abundant in healthy RMG and decreases in uveitis." (PMID 40001591, 2025). "Notably, MRC2 has not yet been described in the retina, in RMG or in the context of uveitis." (PMID 40001591, 2025).
tumor (39 papers, 2009 to 2026). "There was a trend towards upregulation of genes encoding fibroblast activation markers (Col1a1, Mrc2, Acta2) in the presence of tumor-infiltrating CD8+ T cells." (PMID 38259467, 2023). "In line with this, Mafb/Maf editing induced a strong regulation of M1-associated genes (Inos, Ccl2, and Tnfa) and concomitant downregulation of M2-associated genes (Fizz1, Arg1, and Mrc2) in KCs of tumor-bearing mice." (PMID 36821387, 2023). "We also identified and validated one oncogene Mrc2, whose loss could block the tumor cell growth both in vitro and in vivo." (PMID 34815798, 2021). "Low p-values (as in the genes KIAA1614 and MRC2) indicate a significant form of silencing or activation of the genes by methylation that can lead to tumor behavior and prognosis." (PMID 41300918, 2025). "Impairment of a distinct CAFs population limits tumor growth and metastasis, where genetic deletion of the Endo180 (MRC2, bSE = 4.3) receptor, predominantly expressed by a population of matrix-remodeling CAFs, profoundly limits tumor growth and metastasis." (PMID 39335478, 2024). "Data are reporting that high expression of MRC2 produces tumor growth and is related to metastasis; thus, it usually associated with worse prognosis in several cancers." (PMID 36613987, 2022). "Firstly, we evaluated the ability of S100A4 and MRC2 as biomarkers by analyzing tumor and healthy prostatic regions with immunohistochemical techniques (n = 11)." (PMID 36613987, 2022). "Apart from Mrc2, we identified some other DEGs between the BRCA1 deficient luminal cells and tumor cells." (PMID 34815798, 2021). "In this case, we determined a significant difference for S100A4 and MRC2, detecting an increased expression of both molecules for the tumor group, but conclusive results could only be obtained for MRC2." (PMID 36613987, 2022). "This upregulated expression was validated by RT-qPCR analysis of cultured tumour cells and tumours cells isolated from in vivo tumours, although it is important to note that expression of both Acta2 and Mrc2 in the D2A1-m12 cells is still substantially lower than expression levels in CAF." (PMID 34112782, 2021). "Next, we examined whether knockout of Mrc2 could also block the tumor cell growth in vivo by implanting the cells into the fat pads of nude mice." (PMID 34815798, 2021). "By carefully checking the expression patterns of MRC2 in histological sections of Brca1 mutant mouse mammary glands and tumors, we found MRC2 is expressed at low level in the basal cells and highly expressed in the tumor cells." (PMID 34815798, 2021). "The expression of both MRC2 and transforming growth factor (TGFβ1) was detected in tumor tissues and adjacent liver tissues from 96 HCCs by immunohistochemistry staining, and it was found that MRC2 expression in HCC tissues was significantly higher than in adjacent liver tissues." (PMID 25162823, 2014). "Promoter methylation analysis demonstrated that MRC2, OLFML2B, and PLAU were differentially and highly methylated in primary tumor cells compared with normal cells." (PMID 37340445, 2023). "In cancer cells expressing the matrix-remodeling CAF receptor Endo180 (MRC2), genetic deletion profoundly limits tumor growth and metastasis." (PMID 37496657, 2023). "Then, MRC2 and S100A4 gene expression analysis was undertaken using tumor and healthy paraffin-embedded prostatic tissue (n = 13)." (PMID 36613987, 2022). "Here we show that genetic deletion of the Endo180 (MRC2) receptor, predominantly expressed by a population of matrix-remodelling CAFs, profoundly limits tumour growth and metastasis; effects that can be recapitulated in 3D co-culture assays." (PMID 34112782, 2021). "Endo180 protein, coded by the MRC2 gene, plays a role in extracellular matrix remodeling and plasticity in tumor cell movement, cooperating with the matrix metalloproteinases." (PMID 33348918, 2020).
tumor (continued). "Ultimately, we identified the CTSK + MRC2 + CAF cluster as an APPCAF cluster that interacts strongly with T cells, which may help regulate different aspects of tumor immune microenvironment (TIME) biology." (PMID 38221616, 2024). "Moreover, MRC2, OLFML2B, and PLAU were differentially and highly methylated between tumor and normal tissues as well as between genders, races and tumor grads." (PMID 37340445, 2023). "Of note, however, the expression level of MRC2, an M2-type immunosuppressive and tumorigenic macrophage–related gene, was most strongly correlated with that of MMP14, also implicating M2-TAMs in MMP14-related tumor progression." (PMID 36052235, 2022).
cancer (33 papers, 2009 to 2026). A tumor composed of atypical neoplastic, often pleomorphic cells that invade other tissues. "Previous bioinformatic analyses of cancer-associated fibroblasts have highlighted MRC2 as a potential biomarker for fibroblasts with antigen-presenting capabilities." (PMID 40001591, 2025). "In pan-cancer transcriptional and clinical data, MRC2 expression was significantly associated with the immune microenvironment such as immune cell infiltration, which is consistent with the functional enrichment analysis." (PMID 37576552, 2023). "Gene-set enrichment analysis analyses were performed to explore the underlying biological process of MRC2 across different cancers." (PMID 36188226, 2022). "Meanwhile, the genetic ablation of MRC2 affects the contractility and viability of cancer associated fibroblasts, limiting tumor growth and metastasis." (PMID 36188226, 2022). "Previously, MRC2 has been proved to participate in the process of EMT associated with cancer progression by disrupting epithelial cell-cell interactions." (PMID 34336102, 2021). "To identify cancer types with a particularly high expression of uPARAP, we initially screened The Cancer Genome Atlas (TCGA) for the mRNA expression of MRC2, the uPARAP encoding gene, in various cancers." (PMID 34768883, 2021). "The urokinase plasminogen activator receptor-associated protein, uPARAP/Endo180 (MRC2 gene) (hereafter designated uPARAP), is an endocytic receptor expressed by migrating cells, including cancer cells, macrophages, fibroblasts and endothelial cells." (PMID 30518756, 2018). "There have been accumulating studies reported that MRC2 expression is increased aberrantly in a variety of cancers and associated with poor prognosis." (PMID 25162823, 2014). "Mannose Receptor C Type 2 (MRC2) has been associated with metastasis in different types of cancers." (PMID 40346322, 2025). "It has previously been observed that the expression of MRC2 is aberrantly upregulated in a variety of cancers and associated with poor prognosis, upregulated in including breast cancer, prostate cancer, hepatocellular carcinoma, as well as head and neck cancer." (PMID 36188226, 2022). "Also, MRC2 contributes to the EMT process associated with cancer progression by disrupting epithelial cell-cell interactions." (PMID 34336102, 2021). "Additionally, the high MRC2 levels in healthy RMG might contribute to maintaining an immunosuppressive retinal environment, as previously shown in murine cancer-associated fibroblasts expressing high amounts of MRC2." (PMID 40001591, 2025). "There have been accumulating studies reporting that MRC2 expression is increased aberrantly in a variety of cancers." (PMID 36188226, 2022). "Meanwhile, MRC2 has an impact on cell migration and invasion involved in tissue repair, cancer progression, and more pathological lymphangiogenesis." (PMID 36188226, 2022). "The Kaplan–Meier (KM) curves were performed to visualize the prognostic value of MRC2 expression levels in above cancers." (PMID 36188226, 2022). "GSEA also points out that the biological processes of MRC2 in different types of cancer are involved in the activation of immune response and adaptive immune response." (PMID 36188226, 2022). "In our study, we evaluated the MRC2 expression and prognosis-related significance across 33 cancer types based on Cancer Genome Atlas (TCGA) data." (PMID 36188226, 2022). "There is increasing evidence that MRC2 interferes with lymphatic endothelial cells VEGFR-2 and VEGFR-3, which are associated with cancer progression and metastasis to lymph nodes and distant organs." (PMID 36188226, 2022). "Current research has focused on the relationship between MRC2 and tumor immune response and critically analyzed the role of MRC2 in cancer immunity and its potential combination with cancer immunotherapy." (PMID 36188226, 2022).
cancer (continued). "MRC2 (Mannose Receptor C Type 2) is a constitutively recycling endocytic receptor belonging to the mannose receptor family, which has been found to be closely involved with cancer metastasis." (PMID 25162823, 2014). "Quite a few studies have attempted to clarify the regulatory role of MRC2 in various cancers." (PMID 37498303, 2023). "In conclusion, we found that MRC2 could be a prognostic indicator for certain cancer and is critical for tumor immune microenvironments." (PMID 36188226, 2022). "Previous studies also suggest that in most solid tumors of epithelial origin, expression of MRC2 is reported to be predominantly restricted to cancer-associated fibroblasts (CAFs) with little or no expression by the tumor cells." (PMID 36188226, 2022). "MRC2 expression levels were altered in a variety of cancers." (PMID 36188226, 2022). "However, little systematic research has been focused on the MRC2 expression features and prognosis in pan-cancers." (PMID 36188226, 2022). "Our study aimed to evaluate MRC2 expression pattern, clinical characteristics and prognostic significance in 33 cancers, explore the relationship between MRC2 and immune-related characteristics, and assess the prediction of MRC2 for the immunotherapeutic response." (PMID 36188226, 2022). "Besides, though extensive research has been carried out on the relationship between immune therapy and ECM, no related study clarified the immune-related characteristics and immunotherapeutic prediction of MRC2 in different cancers." (PMID 36188226, 2022). "On the other hand, PLAUR and MRC2 are involved in the activation of plasminogen and, although the benefit of targeting these proteins in fibrosis remains to be fully demonstrated, encouraging results have been reported for cancer settings." (PMID 36531712, 2022). "We also found the expression of MRC2 could be detected in some normal and cancer tissues of human breast samples collected in public database, the human protein atlas." (PMID 34815798, 2021). "Therefore, we consider that LINC00909 executes its oncogenic functions, such as promoting cancer cell proliferation, migration, and invasion, by influencing MRC2 expression." (PMID 34336102, 2021). "However, the clinical and immunotherapeutic value of MRC2 in pan-cancers remains controversial." (PMID 36188226, 2022). "Therefore, further analysis at the single-cell level in one or several cancer types may be performed in the future, followed by a more in-depth analysis of MRC2." (PMID 36188226, 2022). "In addition, MRC2 is involved in chemotaxis and invasion and could be important for the acquisition of those traits by cancer cells." (PMID 20885998, 2010). "uPARAP/Endo180, also known as mannose receptor C-type 2 (MRC2) or CD280, is overexpressed in various cancers and functions as a recycling endocytic receptor that facilitates cell migration and the uptake of collagens for intracellular degradation." (PMID 41479915, 2025). "Through the coordination with membrane-associated glycoproteins—including CD44, epidermal growth factor receptor (EGFR), integrins, CD280 (uPARAP/Endo180/MRC2), and CD276, CD147 orchestrates intracellular signaling events that drive cancer cell metabolic adaptation." (PMID 41479915, 2025). "The transcriptomic analysis confirmed mRNA expression of classical epithelial markers (cytokeratins, claudins, EpCAM, E-cadherin) in the SW480 cancer cell mono-spheroids and typical fibroblast markers (ACTA2/α-SMA, FAP-α, PDGFR, and MRC2) in the fibroblast mono-spheroids." (PMID 39011470, 2024). "The MRC2, which is involved in homeostatic maintenance and ECM remodeling, plays a role in physiological (embryonic development, wound healing, tissue repair) and pathological conditions (cancer, inflammation)." (PMID 36188226, 2022). "Interestingly, several genes were known to be regulated by the TGFβ pathway (e.g., BMF, COL4A4) and/or expressed in several cancers (e.g., HOTAIR, MRC2, POSTN, SPARC)." (PMID 34830779, 2021).
cancer (continued). "Our results suggest that radiation-induced increases of FN1, CTSD, GSN, and MRC2 may play radioresistant and negative roles in cancer therapy." (PMID 26056562, 2015).
infection (3 papers, 2012 to 2021). The state of being infected such as from the introduction of a foreign agent such as serum, vaccine, antigenic substance or organism. "Interestingly, MRC2 gene expression has also been shown to increase in spleen cells of mice after infection with Plasmodium spp." (PMID 33536090, 2021). "Next, we found increased mRNA expression and activity levels of Arg1, mRNA expression of Fizz, Chi3l3, Cd209d, Cd209e, Mrc2 (Cd206), Marco, Il13, Saa1 (Serum amyloid A1 protein), Ccl17, Ccl19, Ccl20, Ccl22, and Ccl24 in Stat2−/− mice compared to WT mice during super-infection." (PMID 30337919, 2018). "Consistent with the results from microarray experiments, PR/8 infection significantly decreased the mRNA levels of CLEC7A (Dectin 1), macrophage scavenger receptor 1 (MSR1), CD36, and the mannose receptor C type 1 (MRC1) but did not change the expression of MRC2." (PMID 22396727, 2012).
bacterial infections (1 paper, 2023). "MRC1 and MRC2 are crucial components of the innate immune system, and they contribute to defense against pathogenic bacterial infections." (PMID 37340445, 2023).